IFNG (interferon gamma)
Diseases named in the same sentence as IFNG in open-access papers (continued):
Sharing a sentence is not in itself a finding about the gene and the disease.
infection (continued). "Identical to these published findings we show here, that in C. pneumoniae-infected TLR2/4 double-deficient BMDM IFNγ only weakly up-regulated the expression of iNOS and failed to induce the secretion of NO, since the infection of these cells with C. pneumoniae did not induce NF-κB." (PMID 22096480, 2011). "It was therefore necessary to examine whether LD infection of the host cells delocalizes the IFNγR chains from the lipid raft microdomains that in consequence might hinder efficient oligomerization of the receptor subunits upon IFNγ mediated stimulation." (PMID 21931549, 2011). "Two-to-three weeks after infection, T-cell immunity develops and antigen-specific T lymphocytes arrive, proliferate within the early lesions or tubercles, and release proinflammatory cytokines such as interferon-γ (IFNγ) that will activate macrophages to kill the intracellular mycobacteria." (PMID 21603213, 2011). "However, upon infection TLR2/4 double-deficient mice displayed a lower frequency of CD4+CD25+Foxp3+ regulatory T-cells in vivo and the frequency of regulatory T-cells was inversely related to the frequency of CD4+IFNγ+ T-cells." (PMID 22096480, 2011). "We hypothesized that the initial burst of Mtb-specific IFNγ responses shortly after SIV infection may reflect a transient perturbation of the local control of infection at the level of the granuloma, resulting in an increase in antigen load due to bacterial replication." (PMID 20224771, 2010). "These genes were also up-regulated with time in the monocyte population alone (in response to IFNγ treatment), suggesting that the expression of these major mediators of cell activation in a complex model of infection may be due primarily to the response of monocytes to IFNγ." (PMID 20339534, 2010). "In addition, approximately 1% of all splenic CD4+ T cells were IFNγ+ at 12 hours after infection." (PMID 18404208, 2008). "In particular, a surge of IFNγ production at 3 to 4 days p.i. was demonstrated to be essential for murine CM, and this may be due to the absence of regulation in IFNγ pathways at early stages in PbA infection." (PMID 18062806, 2007). "After about 28 months of anti-BCG combination therapy with interferon-gamma (IFN-γ), the infection was successfully controlled." (PMID 41668770, 2026). "During the peak of infection, T-cell frequencies across all peptides were similar, but at infection resolution, the frequency of pp65 and gB-specific CD4+IFNγ+ T cells was significantly higher than gL/pUL128L." (PMID 41599037, 2026). "Conversely, the KLRB1+ cluster (cytokine-producing cluster), enriched for cytokine/chemokine genes (CCL5, IFNG, IL32), were depleted during infection." (PMID 41544143, 2026). "In a murine infection model, latency established by a HSV-1 LAT+ strain exhibited more functionally exhausted CD8+ T cells in the TG, as measured by IFNγ and TNFα expression, compared to mice infected with a LAT-null HSV-1 strain." (PMID 40431612, 2025). "In terms of mRNA expression, the cytokines Interleukin 6 (IL-6), Interleukin 8 (IL-8), Interferon Beta (IFN-β), Interferon Gamma (IFN-γ), and Tumor Necrosis Factor Alpha (TNF-α) were significantly upregulated (P < 0.001) to varying degrees following infection." (PMID 40642060, 2025). "In contrast, infection of CoMtb mice induced an increased representation of activated CD4 T cells (primarily defined by CD44 and IFNg) and MDCs at early time points (d17), and this was correlated with decreased bacterial burdens at this time point." (PMID 40736456, 2025). "At 3 days post-infection, BALB/c mice had elevated levels of inflammatory cytokines IFNγ and GZMB and elevated levels of the anti-inflammatory cytokine IL-10 at 6 days post-infection." (PMID 40733664, 2025). "As a result, infection-upregulated genes were expressed at higher levels in the SFV/TNFα group (Cluster 1) and in the SFV/IFNγ group (Cluster 3)." (PMID 40547518, 2025).
infection (continued). "Following 1e5 PFU infection, at 3 dpi in the liver, PEP-R619W M-cNK cells (CD11b+ CD49b+ CD49a− NK1.1+) have higher expression of (i) IFNγ, (ii) T-bet, (iii) granzyme B, and (iv) perforin, compared to PEP-WT M-cNK cells (i–iv)." (PMID 40791464, 2025). "Specifically, ILC1 responds to co-stimulatory signals from IEC, which are mediated by the microbiota, and produces interferon-gamma (IFN-γ), In contrast, ILC2 secretes IL-13 upon infection, targeting crypt ISCs to promote the differentiation of goblet cells." (PMID 40098959, 2025). "In contrast, infection led to an upregulation of the pro-tumorigenic gene Arid5a, with the highest expression observed in the SFV/IFNγ group." (PMID 40547518, 2025). "While IFN1 was found to be present during early infection and induces the release of other beneficial cytokines, blocking IFN1 signaling was also shown to improve fungal clearance and IFNγ production." (PMID 39807873, 2025). "Under co-culture conditions, after OVV-01 infection of A673 and K562 cells (MOI=2 and MOI=5), the secretion of IFNγ by TCR-T cells was significantly increased (21%, 3.67%, respectively) compared to the control group (uninfected)." (PMID 40873562, 2025). "Because IFNγ signaling significantly increases MHC-II expression via the IRF-1/CIITA axis, with peak serum IFNγ levels observed at 16 days post-MHV68 infection, the expression of MHC-II by germinal center B cells was measured next." (PMID 41263556, 2025). "Given the enhanced M-cNK IFNγ expression and the overall increased IFNγ concentration in our PEP-R619W mice, we next wanted to determine if IFNγ and/or IFNγ-signaling was necessary for survival and weight retention during MHV A59 infection." (PMID 40791464, 2025). "Furthermore, SFV infection of cancer cells downregulated several migration- and invasion-associated genes in macrophages (e.g., Mmp8, Mmp10 and Mmp12), particularly in the SFV/IFNγ group, suggesting that this approach may inhibit cancer cell dissemination and metastasis." (PMID 40547518, 2025). "Similar to the neonatal-infected mice, we bled the adult-infected mice at 16 wks post infection and performed a gB peptide restimulation of the CD8 + T cells to measure antigen-specific production of IFNγ." (PMID 40720547, 2025). "Pro-inflammatory cytokines, such as IL-8, GM-CSF, and interferon-gamma (IFN-γ), inhibit both intrinsic and extrinsic apoptotic pathways in neutrophils, promoting prolonged survival at infection sites." (PMID 40951140, 2025). "Infection of BALB/c and STS mice resulted in 10-500× increase of production of IFNγ IL-2, IL-4, IL-6 and IL-10 by their splenocytes, whereas strain O20 splenocytes did not produce any of these cytokines except IL-6." (PMID 41164189, 2025). "We observed that nine biomarkers (fractalkine, IFNγ, IL-5, IL-6, IL-10, IL-12, IL-13, IL-21, and TNFα) had significantly increased levels post-infection with subtype C HIV-1 compared to the pre-infection levels." (PMID 40862133, 2025). "Blood samples were collected within one year post infection, and the horses’ peripheral blood mononuclear cells were stimulated with a WNV capsid protein mix to detect interferon-gamma-producing cells." (PMID 40867680, 2025). "Specifically, natural infection and wP vaccination induce the rapid proliferation of the CD4+ tissue-resident memory (TRM) T cells in respiratory tissues, which secrete interferon gamma and IL-17." (PMID 40709171, 2025). "These OT-I T cells were then transferred into WT or IFNγ-/- hosts, followed by Lm-OVA or PbA-OVA infection." (PMID 40163479, 2025). "In sheep, rZH548ΔNSs:FPPRV also induced a robust IFNγ production against PPRV at 14 and 21 days post-infection (dpi)." (PMID 41150427, 2025). "We also included combinations of stimuli to mimic bacterial response to infection (smooth lipopolysaccharide/sLPS, Pam3CSK4/P3C, CD40 ligand + IFNγ + sLPS/CIL, interleukin-10 + sLPS/LIL10)." (PMID 40866338, 2025).
infection (continued). "Infection with L. monocytogenes led to a significant increase in the mRNA levels of IL6, CXCL8, TNF, and IFNG (p < 0.01 for IL6, p < 0.001 for other cytokines), along with a significant decrease in transcription level of IL10 (p < 0.001)." (PMID 41376047, 2025). "In the brain, there were significantly higher levels of interferon gamma–induced protein 10 (IP‐10 or CXCL10), IFNγ and tumor necrosis factor in the SFV + IAV–coinfected mice compared with SFV‐ and IAV‐only infections at 10 dpi." (PMID 39971320, 2025). "These bacteria establish chronic reservoirs that evade immune responses, including interferon-gamma (IFN-γ) signaling, and continuously reseed the intestinal lumen via bile, perpetuating cycles of infection and shedding." (PMID 41184906, 2025). "It is well known that IFNγ, produced by TH1-polarized CD4+ T cells, plays a central role in controlling Plasmodium blood-stage infection." (PMID 40746561, 2025). "In immunocompetent mice, we observed increased mRNA levels of interferon gamma (IFNγ), tumor necrosis factor alpha (TNFα), PTGS2/COX-2, and interleukin (IL)-17A at the beginning of infection." (PMID 40586570, 2025). "The heightened infection risk in GD may be attributable to dysfunction of immune cells, including monocytes, macrophages, dendritic cells, T cells, and B cells, as well involvement of cytokines, such as MCP1/CCL2, CXCL8/IL8, CXCL1, IL-1β, IFNγ, and TNFα, are implicated in GD progression." (PMID 40980139, 2025). "Administration of anti-IL-10 to iron-loaded Tim3−/− animals or to splenocytes ex vivo restored IFNγ expression of CD4+ T cells and improved infection control under high iron conditions." (PMID 40939292, 2025). "Conversely, upon losing control of the infection, T cells would differentiate toward effector memory (TEM) cells with reduced IL-2 production and increased IFNγ and TNF secretion." (PMID 41159744, 2025). "Pathways including IFNA and IFNG responses were shown to be significantly upregulated in both PAMs and PIMs upon NC134 or NC174 infection (green squares)." (PMID 41169353, 2025). "Further, analysis of cytokine production revealed similarly upregulated CD4+IL-17A+, CD4+IFNγ+, and CD4+IL-22+ T cells in the colons of RORγtK256R/K256R and WT mice after infection." (PMID 39504243, 2024). "Our data also show that IL18 levels are also significantly higher in N. caninum-infected mice at 4 h post-infection, and IL18 levels generally track with IFNγ (Data Set S1)." (PMID 39445806, 2024). "Not surprisingly, animals deficient for COX2 showed a strong increase in viral titers in the lung after infection with influenza A virus, whereas the concentrations of cytokines such as TNF, IL-1β, IL-6 and IFNγ were reduced in bronchoalveolar lavage fluid." (PMID 39107476, 2024). "Next, Ifnγ−/− mice were infected with C. parvum expressing the nLuc reporter and injected intraperitoneally with PBS or 10 μg EGF on days −1, 2, and 5 of infection and every fifth day thereafter." (PMID 38995074, 2024). "Ifne-/- mice have fewer CD69+IFNγ+ double-positive and CD69+IFNγ- single-positive NK cells in the upper FRT during infection compared to WT controls." (PMID 38263527, 2024). "The secreted form of the protein encoded by this gene is known to be increased in response to stress and inflammatory mediators such as IL1B, IFNG, or TNF, as well as upon infection with bacteria and viruses such as SARS-CoV-2." (PMID 39337540, 2024). "Analysis of NPFF+ and IFNγ+ BAL neutrophils showed that they clustered into separate populations at steady state and after infection." (PMID 38295799, 2024). "Although both Interferon-γ (IFNG) and IL-1B were up-regulated with direct RRV infection of MM chondrocytes, the inclusion of FLS altered their expression." (PMID 39028255, 2024). "In the early stages of infection, it is common to observe a systemic TH1 response involving the production of cytokines, such as interferon-gamma (IFN-γ)." (PMID 38338740, 2024).
infection (continued). "We found that patients with shorter hospitalization have more robust of both IFNγ+CD4+ and CD8+ T cell responses than those with extended hospitalization (P < 0.05) during the early phase post-infection (7–14 dps)." (PMID 38811527, 2024). "Antigen specificity, IFNγ production, and T cell activation were assessed in the whole lung digest, bronchoalveolar lavage (BAL), and the TBLN 7 days after infection." (PMID 39205245, 2024). "On one hand, an IFNγ-dominant CD8+ T cell response is suggested to contribute to protective immunity in both murine and human VL, potentially aiding in control of the infection." (PMID 39781380, 2024). "In this study, MMP13 represented a reliable target gene to evaluate pro-inflammatory status of macrophages in horses because IFNγ and EIAV infection considerably increased its expression." (PMID 39772115, 2024). "At 24 h post infection in 31 human lung explant tissue samples, key cytokines such as interleukin (IL)-6, IL-10, tumor necrosis factor-alpha (TNF-α), and interferon-gamma (IFN-γ) were upregulated." (PMID 39456722, 2024). "We examined IFNγ-, IL17A-, and IL17F-producing T cell subsets, including γδ+, CD4+, and CD8+ T cells, after 14-days post-infection." (PMID 39475280, 2024). "ILC1s act during the earliest phases of this response, as illustrated by ILC1 IFNγ production in response to MCMV infection, which is detectable as early as 12 hours post infection." (PMID 38684766, 2024). "The significantly downregulated genes (NEAT1, TPM3, ZNHBA, CKLF, and OSBPL8) and the upregulated genes (ITMZC, IFNG, CD69, DNAJB9, and LYST) in NCAM1+FCGR3A+dNK cells after infection were also analyzed." (PMID 38730500, 2024). "Immunizing C3H/HeN mice with recombinant YbgF resulted in the proliferation of IFNγ secreting CD4+ and CD8+ T cells and fewer bacteria in the spleen, liver, and lungs following infection with R. rickettsia." (PMID 38567021, 2024). "Heterologous infection or immunization priming also induced an increase of secondary effector CXCR5– Th1 cells that expressed both TBET and IFNγ, which were maintained at a higher magnitude even at later timepoints." (PMID 39283916, 2024). "These cells were functionally potent, produced high levels of IFNγ and TNF and efficiently protected animals from secondary infection." (PMID 39107476, 2024). "For IFNγ blockade, mice received isotype control or 0.2 mg anti-IFNγ (XMG1.2, BioXCell) in 100 ul of PBS intraperitoneally a day before infection." (PMID 38295799, 2024). "These examples highlight how local infections alter monocyte cell fate during hematopoiesis, and how IL12 and IFNγ production can impact innate cell populations prior to systemic inflammatory responses to T. gondii." (PMID 39445806, 2024). "IFNα and IFNγ transcription levels in PRRSV-infected PAMs were upregulated at 12 and 24 h post-infection, and significantly down-regulated at 36–72 h post-infection." (PMID 38510257, 2024). "In this study, we uncover that during acute stages of infection, T. gondii relies on the MYR translocon complex to prevent premature egress and host cell death in human cells stimulated with IFNγ following infection." (PMID 39292011, 2024). "Remarkably, similar to our findings with IkkαLyve-1 mice, recent work revealed that IFNγ−/− mice exhibit improved morbidity and survival following IAV (PR8) infection." (PMID 39007717, 2024). "Not only have type-1 interferons been found to inhibit protective cytokines (IFNγ, TNF, IL-12, IL-1α, IL-1β), but they also contribute to spread of infection and lung inflammation by increasing accumulation of myeloid cells." (PMID 39717773, 2024). "Concurrently, the cytokine expression profile demonstrates a gradual elevation in IL5, IL13, IFNγ, and TNF, indicating an increasingly complex immunomodulatory environment according to the infection dose." (PMID 39621794, 2024).
infection (continued). "Whole body 18FDG-PET-CT imaging showed that IFNγ promotes SARS-CoV-2 induced pulmonary disease and IL-10 dampens the size, activity, and duration of lung lesions induced after infection." (PMID 38950078, 2024). "Two-way ANOVAs revealed significant interactions between EcoHIV infection and B/F/TAF treatment for IFNγ, IL-7, IL-10, and RANTES." (PMID 38786105, 2024). "The Th1 response is characterised by the secretion of interferon-gamma (IFN-γ) and interleukin 12 (IL-12) cytokines, which have been demonstrated to be released by infection of M. tuberculosis." (PMID 40303082, 2024). "Already at day one post-infection, high frequencies of IFNγ-, TNFα- and granzyme B (GrzB)-producing CD8+ T-cells were detectable reaching the maximum at day one or three post-infection before declining." (PMID 39472590, 2024). "In contrast, efficient protection against RSV infection correlates with local cellular immunity in the lungs, such as IFNγ producing CD4+ T-cells, which have been identified as a protective measure against infection and subsequent lung inflammation." (PMID 39472590, 2024). "In the case of a clinically evident infection, there is a local immune response involving CD8+ cytotoxic T lymphocytes and T helper 1 CD4+, which produce interleukin 2 (IL-2) and interferon gamma (IFN-gamma) and recognize the viral protein E6, E7, and E2." (PMID 36851321, 2023). "Although previous infection played an important role in driving IgG and IFNγ responses, we were interested to investigate whether peak post-vaccination responses are associated with subsequent breakthrough infection, irrespective of factors that may influence the level of response." (PMID 37655880, 2023). "Within splenocytes, expression of IFNγ, TNFα, IL17, IL13, IL10, and TGFβ were changed by both infection and vaccination within CD4 and CD8 T cells and regulatory T cells." (PMID 36799886, 2023). "It has been also suggested that IFNγ-dependent activation of innate immunity during the recall response to ASFV, as well as a broad cytotoxic response during the first hours of infection, are critical immune components for protection against ASFV." (PMID 36680273, 2023). "Very early Ifnγ produced by memory CD8 T cells and NK cells has been observed in previously infected animals following a repeat infection with the same strain of IAV." (PMID 37842651, 2023). "Long COVID diagnosis was less likely with factors including O blood group, higher occupational status, physical activity, three vaccine doses, strong SARS-CoV-2-S-reactive IFNγ-producing-CD8+ response, and infection during the Omicron period." (PMID 37896992, 2023). "Unconventional T cells and innate lymphoid cells, particularly NK cells, were the dominant producers of early Ifnγ, while CD4 and CD8 T cells were the main producers by day 10 post-infection." (PMID 37842651, 2023). "Infection of APCs with opsonized EBs enhanced expression of chemokines CXCL1, 2, 5 and pro‐inflammatory cytokines IL1β and IFNγ and TNF mRNA." (PMID 38441219, 2023). "Luminex analysis confirmed that remdesivir potently blocked SARS-CoV-2-induced cytokine release from ALI lung organoids at 48 hours post-infection, particularly evident for GCSF, IFNG, IL6, CXCL10, CCL2, and TNFA." (PMID 37205380, 2023). "Upon lethal infection with SPN, IFNγ expression by NK cells increased at 40 hours in the lungs at equal levels between endogenous and transferred cells in the same mouse." (PMID 37486946, 2023). "In the skin of the Vγ4/6−/− mice, there was a significant increase in the frequency of activated IFNγ-producing CD8+ T cells compared to FVB/N controls under homeostatic conditions, which were exacerbated during infection." (PMID 37644007, 2023). "Similar findings have been observed in mouse models of IAV infection demonstrating that IFNγ+ CD4 and CD8 T cells can protect mice from challenge infection." (PMID 37842651, 2023).